SLC7A11 (solute carrier family 7 member 11)
Diseases named in the same sentence as SLC7A11 in open-access papers (continued):
Sharing a sentence is not in itself a finding about the gene and the disease.
tumor (continued). "Disulfidptosis is a recently identified programmed cell death in tumor cells overexpressing SLC7A11 under glucose starvation." (PMID 37864127, 2023). "The relationship between SLC7A11 and tumour immunity, immune checkpoints, and immune cell infiltration was studied using R language." (PMID 37880315, 2023). "IFN-γ released by immunotherapy-activated CD8+T cells down-regulates the expression of SLC3A2 and SLC7A11, inhibits cystine uptake in cancer cells, and enhances ferroptosis specific lipid peroxidation in tumor cells." (PMID 37600785, 2023). "Using glutaminase inhibitors on tumor cells with high expression of SLC7A11 increases cell mortality in an independent GSH-GPX4 pathway." (PMID 37329384, 2023). "Mechanistically, mounting evidence suggests that SLC7A11 is overexpressed in many cancers; in particular, multiple factors reverse tumor suppression by stabilizing or upregulating SLC7A11 in sorafenib- and cisplatin-resistant cells." (PMID 37408372, 2023). "Another study indicated that the suppression of the ferroptosis-related gene SLC7A11 seems to be connected with many kinds of tumor suppressor mechanisms, which results in an increased sensitivity to ferroptosis." (PMID 37212877, 2023). "BAP1, as a tumor suppressor, promotes ferroptosis and inhibits cancer cell growth by inhibiting SLC7A11." (PMID 37299036, 2023). "In conclusion, these results suggest a close association between the expression level of SLC7A11 and the sensitivity of ACC patients to anti-tumor drugs, implying a potentially significant role of SLC7A11 in the treatment of ACC." (PMID 37919768, 2023). "What should be noted is that the promotion of SLC7A11 overexpression on tumor growth and progression is undertaken in part by reducing ferroptosis." (PMID 36903458, 2023). "The deubiquitinating enzyme OTUB1 enhances the sensitivity of tumor cells to erastin-induced ferroptosis by stabilizing the proteasome-dependent SLC7A11." (PMID 36369321, 2023). "After verifying the therapeutic effect of ZPG@H in vivo, the expression of GPX4 and SLC7A11 in tumor tissues suffering from ferroptosis was examined using IHC staining." (PMID 37206228, 2023). "There was good concordance between SLC7A11 (which encodes xCT), NQO1, GCLC and GCLM median expression levels across tumours, providing an ‘antioxidant signature’ associated with the NRF2 transcriptional program." (PMID 38168428, 2023). "SLC7A11 inhibits cell iron-related death and promotes tumour radioresistance to achieve malignant tumour progression." (PMID 37829798, 2023). "More importantly, sulfasalazine (SAS), an FDA-approved anti-inflammatory agent targeting SLC7A11, induces massive lipid peroxidation and results in a significant decrease in tumor volume in vivo." (PMID 37460542, 2023). "SLC7A11 has been described as a key regulator of disulfidptosis, and a therapeutic strategy based on GLUT inhibition-induced disulfidptosis has shown promise in tumor patients with high SLC7A11 levels." (PMID 37427103, 2023). "have found that photon RT and ICIs together suppress SLC7A11 in a manner that promotes tumoral lipid oxidation and ferroptosis, boosting the anti-tumor effect." (PMID 37777634, 2023). "Our findings reveal that SLC7A11 expression level dictates cancer cells’ sensitivity to oxidative stress and suggests a context-dependent role for SLC7A11 in tumor biology." (PMID 37339981, 2023). "Reduced glucose availability in SLC7A11 high tumor cells leads to disulfide stress, which accelerates cell death." (PMID 37598126, 2023).
tumor (continued). "Activated CD8+ cells, for example, induce tumor cell ferroptosis by secreting interferon γ (IFNγ), which subsequently downregulates SLC7A11 and upregulates ACSL4 in cancer cells." (PMID 36658724, 2023). "In particular, the reduced expression of genes, which encode for Xc system proteins, such as SLC7A11 and SLC3A2 causes the increase in ROS-mediated lipid peroxidation and subsequent ferroptosis, even in tumor cells that are more resistant to drug treatments." (PMID 38139106, 2023). "At present, omics studies have found that the ferroptosis regulatory gene SLC7A11 can reduce the abundance of NK cells and inhibit anti-tumor immunity." (PMID 37369681, 2023). "Overall, these results suggest that elevated expression of SLC7A11 and ferroptosis evasion in tumor cells are inversely correlated with clinical prognosis and antitumor immunity in HCC." (PMID 37132587, 2023). "Studies from cancer found that CD8+ T cells can exert their tumor suppressive effects by secreting interferon-gamma (IFNγ) to mediate the downregulation of SLC7A11(Recombinant Solute Carrier Family 7, Member 11)-triggered ferroptosis in tumor cells." (PMID 38127902, 2023). "Recently, a growing number of studies have highlighted the role of Slc7a11 overexpression in partially promoting tumor growth by inhibiting ferroptosis, suggesting that Slc7a11 exhibited antiferroptosis function during malignant progression." (PMID 37424906, 2023). "Some studies have shown that SLC7A11 can affect tumour immune escape and the anti-tumour immune response by regulating intracellular redox balance and tumour cell metabolism and growth." (PMID 37880315, 2023). "SLC7A11 is overexpressed in multiple human cancers and promotes tumor growth by suppressing ferroptosis, a form of iron-dependent regulated cell death induced by excessive lipid peroxidation at cellular membranes." (PMID 38023731, 2023). "We further showed that high overexpression of SLC7A11 promotes primary tumor growth but suppresses tumor metastasis, likely because metastasizing cancer cells with high overexpression of SLC7A11 are particularly vulnerable to oxidative stress." (PMID 37339981, 2023). "CD8+ T cells induce lipid peroxidation and ferroptosis through the downregulation of SLC3A2 and SLC7A11 levels in tumor cells by secreting IFN-γ, thereby mediating effective antitumor responses." (PMID 37545500, 2023). "Given the range of roles that SLC7A11 plays in tumour development, the development of oncology therapies targeting SLC7A11 is clinically significant." (PMID 37919768, 2023). "Disulfidptosis and the disulfidptosis-related gene SLC7A11 have recently attracted significant attention for their role in tumorigenesis and tumour management." (PMID 37919768, 2023). "In vivo, CEBPG knockdown–induced inhibition of xenograft tumor growth was also significantly rescued by SLC7A11 restoration, consistent with that in vitro." (PMID 37210575, 2023). "SLC7A11 is a multifunctional protein that functions in cellular redox homeostasis and tumor malignancy through the activation of the antioxidant glutathione (GSH)." (PMID 37174663, 2023). "Recent studies have established ferroptosis as a key tumor-suppression mechanism and have shown that SLC7A11 overexpression in cancer cells promotes tumor growth at least partly by suppressing ferroptosis." (PMID 37339981, 2023).
tumor (continued). "Considering the high relevance of NADPH to metastasis, we examined the effects of low, moderate, or high SLC7A11 expression on metastasis (as well as on primary tumor growth)." (PMID 37339981, 2023). "Here, the authors show that the expression level of SLC7A11 leads to different outcomes depending on context, so high expression promotes primary tumour growth but promotes disulfide stress under oxidative stress conditions and impairs metastasis." (PMID 37339981, 2023). "IFN-γ secretion notably downregulates the expression of SLC3A2 and SLC7A11 genes in tumor cells, leading to reduced cysteine intake, enhanced lipid peroxidation, and subsequent ferroptosis." (PMID 38562992, 2023). "SLC7A11 expression was positively associated with the expression of immune checkpoint genes (NRP1, TNFSF4, TNFRSF9, and CD276) and tumour mutation burden." (PMID 37919768, 2023). "We further show that high overexpression of SLC7A11 promotes tumor growth but suppresses tumor metastasis, likely because metastasizing cancer cells with high expression of SLC7A11 are particularly susceptible to oxidative stress." (PMID 37339981, 2023). "SLC7A11 also plays an important role as a catalytic subunit of xCT in resisting oxidative stress, inhibiting cell iron-related death, and promoting tumour metastasis." (PMID 37829798, 2023). "m6A methylation-repressed tumour ferroptosis also depends on the inhibition of SLC7A11 deadenylation and enhancement of SLC7A11 stabilization." (PMID 36859310, 2023). "ACC patients with high expression of SLC7A11 exhibit increased sensitivity to certain anti-tumor drugs (YK-4-279, tozasertib, docetaxel, vinblastine and so on), suggesting an important role for SLC7A11 in the treatment of ACC patients." (PMID 37919768, 2023). "SLC7A11-mediated cystine uptake plays an important role in antioxidant defense, including ferroptosis mitigation, which is beneficial for tumor growth, and SLC7A11 is overexpressed in multiple human cancers." (PMID 37339981, 2023). "Radiation-induced ATM activation is also an important source of IFN-γ, which synergies with IFN-γ derived from CD8+T cells to inhibit SLC7A11 and increase ferroptosis in tumor cells." (PMID 37600785, 2023). "Then, we analyzed the levels of CEBPG and SLC7A11 in these orthotopic tumor tissues by IHC staining." (PMID 37210575, 2023). "Tumor cells with higher expression of SLC7A11 were more resistant to arsenic trioxide, parthenolide, and raloxifene." (PMID 37940859, 2023). "Numerous studies have confirmed that the miR-143-3p/SLC7A11 axis is involved in various tumor progression." (PMID 37045929, 2023). "In this process, interferon-γ (IFNγ) derived from activated CD8+ T cells has been shown to defer the expression of SLC3A2 and SLC7A11, inhibiting tumor cell cystine import and sensitizing tumor cells to ferroptosis." (PMID 37840106, 2023). "The most direct proof is that NRF2 has been shown to upregulate SLC7A11, thereby protecting tumor cells from ferroptosis." (PMID 37488128, 2023). "In our previous pan-cancer analysis of SLC7A11, we found that the expression pattern, prognostic value, and its correlation with immune regulation genes, tumor microenvironment, and RNA modification genes in BLCA were highly similar to those in HCC." (PMID 38132439, 2023).
tumor (continued). "Studies have found that SLC7A11 is a key target gene of BAP1, and BAP1 inhibits the expression of SLC7A11 by reducing H2Aub on the SLC7A11 promoter, promoting the occurrence of ferroptosis, and then inhibiting tumor growth." (PMID 36874967, 2023). "And the detection of ferroptosis‐associated markers in xenograft tumor samples with USP5 overexpression also showed that ACSL4 decreased, and SLC7A11 increased." (PMID 37492786, 2023). "We found that, although the expression levels of SLC7A11 in tumor tissues were elevated compared to normal tissues in almost all types of cancer, its relationship with the tumor microenvironment varied greatly across different cancer types." (PMID 38132439, 2023). "SLC7A11 is highly expressed in tumour samples and the ectopic expression of SLC7A11 inhibits by p533KR-induced ferroptosis in human cancer cells." (PMID 38152394, 2023). "Clear cell renal cell carcinoma (ccRCC): As a tumor suppressor, the H2A DUB BRCA1-associated protein 1 (BAP1) suppresses tumorigenesis by inducing ferroptosis through suppression of SLC7A11 in ccRCC." (PMID 38072908, 2023). "It is known that the xCT (SLC7A11) molecule is involved in tumor growth, chemo- and radiotherapy resistance, and poor clinical outcomes." (PMID 36672272, 2023). "Although the substrate-specific subunit SLC7A11 of the system XC− is expressed significantly, ferroptosis induced by the system XC− inhibitor can only be achieved in a small number of tumor cell lines." (PMID 37181755, 2023). "Our findings suggest that SLC7A11 expression levels dictate its context-dependent roles in mediating cancer cells’ oxidative stress responses and in tumor biology." (PMID 37339981, 2023). "The pan-cancer analysis showed that the 5-year OS of the SLC7A11-high group was lower than that of the SLC7A11-low group for many tumours (p < 0.05)." (PMID 37880315, 2023). "In summary, SLC7A11 can influence tumour progression, drug sensitivity, immune infiltration, and the ability to migrate and invade distant sites by modulating cysteine/glutamate transportation in the ACC." (PMID 37919768, 2023). "During tumor growth, tumor cells upregulate the expression of SLC7A11 and maintain a high cystine uptake rate." (PMID 37552314, 2023). "SLC7A11 has also been involved in the promotion of tumor proliferation by enabling the removal of lipid peroxides and inhibiting ferroptosis." (PMID 37298344, 2023). "Inhibiting SLC7A11 can enhance the attack of tumour cells by immune cells and improve the efficacy of immune therapy." (PMID 37880315, 2023). "SLC7A11 repression can be a synergistic anti-tumor mechanism in combination with checkpoint blockade." (PMID 37215113, 2023). "Mechanistically, lncRNA OIP5-AS1 suppressed ferroptosis in cadmium-exposed tumor cells by competitively binding to miR-128-3P and increasing the expression level of SLC7A11, a critical protein for ferroptosis." (PMID 36936418, 2023). "IFN-γ released by CD8+ T cells downregulates the expression of two subunits of the glutamate-cysteine anti-transport system, SLC3A2, and SLC7A11, inhibits the uptake of cystine by tumor cells and promotes tumor cells lipid peroxidation and ferroptosis." (PMID 36060256, 2022). "SLC7A11 controls the uptake of extracellular cystine in exchange for glutamate at a ratio of 1:1, and it is overexpressed in a variety of tumours." (PMID 35804831, 2022). "This is exactly the case in tumor cells with high SLC7A11/xCT expression, which is demonstrated to consume large amounts of NADPH during reduction of imported cystine in recent publication." (PMID 35178349, 2022).
tumor (continued). "Interferon gamma (IFN-γ) secreted by CD8+ cytotoxic T cells promotes lipid peroxidation and ferroptosis by inhibiting the expression of SLC3A2 and SLC7A11, two subunits of system xc− in tumor cells." (PMID 36552652, 2022). "In the tumor microenvironment, SLC7A11 is involved in tumor survival and proliferation through the interaction between immune cells and tumor cells." (PMID 36552652, 2022). "In oral squamous cell carcinoma, miR-375 can inhibit SLC7A11 transcription and regulate tumor resistance." (PMID 35668934, 2022). "The study has reported that the overexpression of SLC7A11 promoted tumor growth by partially inhibiting ferroptosis." (PMID 35874632, 2022). "Under the stimulation of chemotherapeutic drugs, the expression of SLC7A11 in tumour cells is decreased, ROS are increased, and the expression of multidrug-resistant proteins is increased, causing drug resistance." (PMID 35804831, 2022). "Solute carrier family 7 member 11 (SLC7A11) is overexpressed in multiple human tumours and functions as a transporter importing cystine for glutathione biosynthesis." (PMID 35522946, 2022). "When the level of Uc.339 in tumor cells was knocked down, the SLC7A11 expression also decreases and vice versa." (PMID 35399708, 2022). "Meanwhile, the role of SLC7A11 in tumours is highly complex, and its pro-tumour and antitumour activities are obviously different." (PMID 35804831, 2022). "For example, cancer immunotherapy has been shown to enhance the effector function of CD8+ T cells, increase IFNγ release to downregulate SLC3A2 and SLC7A11 expression, resulting in reduced cystine uptake and increased ferroptosis in tumor cells." (PMID 34826064, 2022). "It has been found that the SLC7A11 is upregulated in PDAC tumor tissue, and the increased expression of SLC7A11 has been shown to help the growth of PDAC cells by reversing ferroptosis via upregulating the cysteine." (PMID 36499358, 2022). "Glutamate secreted by SLC7A11 of tumour cells inhibits T-cell activation and stimulates the proliferation of Treg cells to induce intratumoural immunosuppression." (PMID 35804831, 2022). "In the tumour microenvironment, SLC7A11-related interactions between immune cells and tumour cells affect tumour survival and proliferation." (PMID 35804831, 2022). "Mechanistic analyses revealed that BCSC-secreted DKK1 promotes SLC7A11 expression, decreased lipid peroxidation and increased glutathione, leading to diminished tumor ferroptosis and enhanced cancer cell proliferation in lung metastases." (PMID 35296660, 2022). "As expected, SLC7A11 was positively correlated with PNO1 expression in HCC tumor tissues (p < 0.05)." (PMID 36446769, 2022). "Mechanistically, IFNγ significantly downregulated the expression of SLC3A2 and SLC7A11, and then impaired the uptake of cystine by tumor cells, which resulted in enhanced lipid peroxidation and ferroptosis." (PMID 36033530, 2022). "Further, suppressing SLC7A11 expression can result in lipid peroxidation and ferroptosis, thereby promoting tumour cell death." (PMID 35522946, 2022). "Ideal experimental results were obtained; data showed that PX-478 can effectively decrease SLC7A11 expression in tumor tissue and promote the anticancer effect of SAS." (PMID 36439690, 2022). "BAP1 is another tumor suppressor repressing SLC7A11 transcription through H2A histone ubiquitination, which inhibits cystine uptake and GSH biosynthesis, and promotes ferroptosis." (PMID 36552652, 2022). "The loss of SLC7A11 substantially abolishes tumorigenesis while the overexpression of SLC7A11 promotes tumor development through ferroptosis resistance." (PMID 35882850, 2022).